TNF (tumor necrosis factor)
Diseases named in the same sentence as TNF in open-access papers (continued):
Sharing a sentence is not in itself a finding about the gene and the disease.
osteosarcoma (continued). "On the other hand, glutamine catabolizes into ammonia, which promotes mTORC1-independent autophagy and in turn protects cells from tumor necrosis factor-α (TNF-α)-induced death of U2OS osteosarcoma cells." (PMID 34768858, 2021). "LncRNA THRIL has been shown to regulate TNF-α expression and participate in immune response in osteosarcoma." (PMID 34692688, 2021). "LncRNA has been proved to be involved in the immune response of osteosarcoma by regulating the expression of TNF-α." (PMID 34692688, 2021). "M1-like macrophages activated by LPS plus IFN-γ showed suppression on osteosarcoma cell growth, and those effects were mediated by soluble factors secreted by macrophage in a TNF-α/IL-1-independent manner." (PMID 33363016, 2020). "TLR4 was pivotal promoter of inflammation which related NF‐kB and C3 signaling, and then released TNF‐α and ILs, which can induce apoptosis of osteosarcoma cells." (PMID 32822099, 2020). "Both U2OS and U2OS/MTX300 cells were treated with several cytokines that are closely related to osteosarcoma progression, such as TNFα, RANKL, and M-CSF20–22." (PMID 32111827, 2020). "L-MTP-PE administration stimulated the production of cytokines such as TNF-α and IL-6 in patients with osteosarcoma." (PMID 33363016, 2020). "For instance, a preclinical study of osteosarcoma demonstrated that TNF-α administration promoted the de-differentiation of osteosarcoma cells toward a primitive state, which significantly contributed to tumor growth and progression." (PMID 33381449, 2020). "Spontaneous osteosarcomas that arose in genetically-engineered immunocompetent mice also contained abundant TNFα." (PMID 31521127, 2019). "Other cells types, including osteosarcoma cells, fail to produce autocrine TNFα and therefore are only efficiently killed by Smac mimetics when exposed to exogenous TNFα." (PMID 31521127, 2019). "The Smac mimetics LCL161 and GDC-0152 cooperated with TNFα produced by infiltrating immune cells to limit osteosarcoma growth and metastasis in nude mice." (PMID 31521127, 2019). "The clinical responsiveness of individual osteosarcomas to Smac mimetics will presumably be strongly dictated by the ability of the drugs to cooperate with TNFα to trigger apoptotic or necroptotic death of the individual’s cancer cells." (PMID 31521127, 2019). "A subset of Smac mimetics (SM-164, LCL161 and GDC-0152) potently cooperated with TNFα to kill cells from many murine osteosarcomas in vitro, and this toxicity was potentiated by co-treatment with doxorubicin." (PMID 31521127, 2019). "Although the Smac mimetics were effective in vivo, in vitro they only efficiently killed osteosarcoma cells when TNFα was supplied." (PMID 31521127, 2019). "Mice bearing implanted or spontaneous osteosarcomas had around twice as much TNFα in their blood as tumor-free animals." (PMID 31521127, 2019). "Although published data suggest human TNF receptors bind murine TNFα with only slightly lower affinity than human TNFα, the human osteosarcoma cells were significantly more sensitive to Smac mimetics coupled with human than murine TNFα." (PMID 31521127, 2019). "The in vitro sensitivity of the murine and human osteosarcoma cells used to create these tumors depended on supplied TNFα." (PMID 31521127, 2019). "Given the requirement of the inflammatory cytokine TNFα for the anti-osteosarcoma activity of Smac mimetics, we were particularly keen to avoid analgesics with anti-inflammatory activities." (PMID 31521127, 2019). "Hardly any cells that lacked immune cell markers, which presumably were mostly 1029H-Luc osteosarcoma cells, contained TNFα." (PMID 31521127, 2019).
osteosarcoma (continued). "Serum TNFα levels were documented to be elevated in osteosarcoma patients, with concentrations reflecting disease progression and primary tumor size." (PMID 31521127, 2019). "Although this difference was not statistically significant, it mirrored published data from humans: the TNFα concentration in sera of osteosarcoma patients was approximately double that in control individuals’ blood." (PMID 31521127, 2019). "Cells from two minimally-passaged human osteosarcomas were quite sensitive to Smac mimetic/TNFα co-treatment, however established human osteosarcoma cell lines varied substantially in their sensitivity to Smac mimetics as sole agents and together with TNFα." (PMID 31521127, 2019). "Inhibiting the TNF‐α/NF‐κB/CUL4B axis significantly inhibited osteosarcoma cell proliferation compared with control cells." (PMID 29377600, 2018). "We found that populations of human osteosarcoma cells, exposed to a clinically relevant 43°C HS had an attenuated NF-κB p65 response to Tumor Necrosis Factor α (TNFα) treatment." (PMID 29708974, 2018). "Our study demonstrates that TNFα upregulated Fgf23 transcript levels in UMR106 osteosarcoma-like cells." (PMID 29807981, 2018). "Using immunoblotting analysis we showed that the exposure to clinically relevant high temperature resulted in time-dependent attenuation of TNFα-induced p65-Ser536 phosphorylation in populations of human osteosarcoma cells." (PMID 29708974, 2018). "In agreement with the previous work, we found that the exposure to clinically relevant high temperature suppressed the population-level NF-κB system responses to TNFα stimulation in human osteosarcoma cells." (PMID 29708974, 2018). "Additional studies reveal that the tumor necrosis factor alpha (TNF‐α)/NF‐κB axis pathway is activated in human osteosarcoma cells." (PMID 29377600, 2018). "By contrast, reverse results were also reported: TNF-α can promote osteosarcoma development by maintaining OS in an undifferentiated state." (PMID 28955228, 2017). "Just as previously reported, high levels of TNF-α can promote osteosarcoma development by maintaining OS in an undifferentiated state." (PMID 28955228, 2017). "TNF-α is a potent cytokine produced primarily by activated macrophages and reported to inhibit the proliferation and differentiation in osteosarcoma cells in vitro." (PMID 27660759, 2016). "We examined the sensitivity of cells from these secondary osteosarcomas to SM-164 and TNFα in parallel with cells from the matching primary tumors." (PMID 27129149, 2016). "The ability of necrostatin to protect sensitive osteosarcoma cells from death triggered by co-treatment with IAP antagonists plus TNFα imply that RIPK1 is an important determinant of sensitivity." (PMID 27129149, 2016). "Previous studies documented average TNFα levels in osteosarcoma patients' blood to be 12 and 28 pg/ml." (PMID 27129149, 2016). "Together these observations suggest that, for TNFα to kill osteosarcoma cells, RIPK1 is required and the activities of cIAP1 and XIAP must be diminished." (PMID 27129149, 2016). "To define the levels of TNFα required for IAP antagonists to kill murine osteosarcoma cells, we performed dose titration experiments using TNFα and the most potent members of the panel of IAP antagonists: GDC-0152 and SM-164." (PMID 27129149, 2016). "Treatment of the sensitive osteosarcoma cells with SM-164 plus TNFα provoked rapid DEVDase activity and exposure of phosphatidyl serine, followed by subsequent plasma membrane disruption." (PMID 27129149, 2016). "Necrostatin reduced or abolished the lethality triggered by treatment of osteosarcoma cells with IAP antagonists plus TNFα, implying that RIPK1 is required for this cell death." (PMID 27129149, 2016). "Levels of TNFα were elevated in the blood of osteosarcoma patients, particularly those with large tumors, and the local concentration at the tumor site would presumably be even higher." (PMID 27129149, 2016).
osteosarcoma (continued). "Interaction between TIMP1 and αvβ3 confers protection against apoptosis induced by TNF-α In human osteosarcoma cell lines." (PMID 23522389, 2013). "We found that in U2OS osteosarcoma cells, TNFα stimulates translocation of RELB and cREL between the nucleus and cytoplasm, with RELB being excluded from the nucleus and cREL accumulating in the nucleus." (PMID 22355351, 2012). "The first such study evaluated three SNPs in the promoter of the Tumor Necrosis Factor-α (TNF) gene in 63 osteosarcoma cases and 111 controls from Spain." (PMID 21437228, 2011). "We have studied the expression of interleukin-6 induced by interleukin-1 β and tumor necrosis factor α in the osteoblast-like cell line MG-63, derived from a human osteosarcoma." (PMID 23675187, 2010). "Mechanistically, PLEK may exert its effects through macrophage-derived cytokine signaling pathways, such as the MIF and TNF pathways previously identified as active in macrophage-osteosarcoma cell communication." (PMID 40895569, 2025). "Furthermore, the expression of ADCK2 was demonstrated to be directly modulated by TNFα in U2OS osteosarcoma cells." (PMID 40565246, 2025). "We recently demonstrated that autologous PBMCs ex vivo loaded with an engineered oncolytic MYXV expressing human TNF (vMyv-hTNF) was an effective therapeutic strategy against murine K7M2 osteosarcoma cells in a lung metastatic preclinical syngeneic murine model, whereas unarmed MYXV was ineffective." (PMID 35251496, 2022). "Previous studies revealed that TNF-α axis pathway was activated in human osteosarcoma cells." (PMID 33436536, 2021). "Functional analysis of the MRGs suggested that TNF and NF-kappa B signaling were significantly enriched in metastasis, two pathways that are known to regulate metastasis in a variety of tumors including osteosarcoma." (PMID 34368151, 2021). "Moreover, Smac mimetic LCL161 was shown to suppress the growth of tumors in osteosarcoma mouse models via a TNF-induced cell death mechanism and consequently lung metastasis." (PMID 33546280, 2021). "While responses appear to be more homogenous than those reported in the previous work using human osteosarcoma cells, we observe that TNFα-induced oscillatory patterns become more robust following recovery from HS in comparison to cells treated under normal conditions." (PMID 32448393, 2020). "In patients with osteosarcoma, IL16 variants were related to higher levels of IL-16 and, consequently, in the effects in the production of other tumor-related inflammatory cytokines, such as TNF-α and IL-1β." (PMID 32915917, 2020). "Furthermore, blocking TNF-α using a soluble receptor (etanercept) to diminish chronic inflammation inhibited osteosarcoma tumor growth." (PMID 33381449, 2020). "For example, we previously showed that TNFα stimulation in human osteosarcoma cells resulted in “all-or-nothing” NF-κB responses following HS, while tissue-level architecture might impose additional spatial constraints." (PMID 32448393, 2020). "This may also indicate that targeting TNFα pathway may benefit osteosarcoma patients with metastasis, as TNFα may increase CBX4 to promote osteosarcoma metastasis." (PMID 32111827, 2020). "Like the implanted tumors, spontaneously arising osteosarcomas that arose in genetically engineered immunocompetent mice also bore high concentrations of TNFα, excluding the possibility that this phenomenon was an artefactual consequence of tumors implanted into nude mice." (PMID 31521127, 2019). "Smac mimetics may therefore benefit osteosarcoma patients whose tumors contain Smac mimetic-responsive cancer cells and TNFα-producing infiltrating cells." (PMID 31521127, 2019). "To model the expected exposure of the human tumor cells to Smac mimetics and TNFα following implantation into nude mice, we compared the extents to which Smac mimetics sensitized the luciferase-tagged KRIB and 143B human osteosarcoma cells to murine versus human TNFα." (PMID 31521127, 2019).
osteosarcoma (continued). "Moreover, it was observed levels of human TNF-α mRNA in a murine cell line co-cultured with MP shed from a human osteosarcoma cell line." (PMID 31137684, 2019). "Immunophenotyping revealed that implanted osteosarcomas, like patient tumors, were heavily infiltrated by immune cells, which our data suggest were responsible for producing most of the intratumoral TNFα." (PMID 31521127, 2019). "This implies that osteosarcoma cells within patients’ tumors may be exposed to enough TNFα to render them sensitive to the lethal effects of Smac mimetics, but direct measurement of TNFα within patients’ tumors would be necessary to confirm this suspicion." (PMID 31521127, 2019). "The spontaneous osteosarcomas, like the subcutaneously implanted tumors, contained abundant TNFα." (PMID 31521127, 2019). "Importantly, TNF‐α/NF‐κB signaling is activated in osteosarcoma cells, increasing the abundance of NF‐κB subunits in the nucleus, thereby activating the expression of CUL4B and regulating the ubiquitination of p21Cip1." (PMID 29377600, 2018). "Importantly, these results provide an opportunity to target the TNF‐α/NF‐κB/CUL4B axis in treating osteosarcoma." (PMID 29377600, 2018). "Given that the TNF‐α/NF‐κB axis was activated in osteosarcoma cells, we next sought to investigate whether the overexpression of NF‐κB subunits in hFOB1.19 cells would cause CUL4B up‐regulation and p21 down‐regulation similar to that of osteosarcoma cells." (PMID 29377600, 2018). "In addition, the overexpression of CUL4B in these cells was able to significantly reverse their growth defects, further suggesting that the TNF‐α/NF‐κB axis mainly contributed to CUL4B expression in osteosarcoma cells." (PMID 29377600, 2018). "In conclusion, our results provide evidence for a potential pathway through which the activation of the TNF‐α/NF‐κB axis positively regulates CRL4BDCAF11 activity, causing p21Cip1 degradation and the disruption of cell cycle progression in human osteosarcoma cells." (PMID 29377600, 2018). "Associations between inflammatory gene polymorphisms (TNF-α 308G/A, TNF-α 238G/A, TNF-β 252A/G, TGF-β1 29T/C, IL-6 174G/C and IL-10 1082A/G) and osteosarcoma (OS) risk remain unclear." (PMID 29228633, 2017). "If the results of this study translate to human osteosarcomas, the levels of TNFα and RIPK1 in patients' tumors may predict their responses to treatment with pan-specific IAP antagonists." (PMID 27129149, 2016). "The osteosarcoma cells were only sensitive to IAP antagonists as a co-treatment with TNFα." (PMID 27129149, 2016). "Recent evidence suggests that osteosarcoma may be a cancer type whose growth and spread is driven by TNFα." (PMID 27129149, 2016). "We therefore explored whether SM-164 and TNFα could enhance the anti-osteosarcoma activity of doxorubicin." (PMID 27129149, 2016). "IAP antagonists cooperated with low doses of TNFα to kill cells from most primary and metastatic murine osteosarcomas, suggesting that members of this class of drugs may be therapeutically useful anti-osteosarcoma agents." (PMID 27129149, 2016). "We therefore speculate that, in these osteosarcoma cells, TNFα/SM-164-induced necroptosis triggered by caspase inhibition resulted from suppression of caspase-8-mediated cleavage of an as-yet unidentified substrate." (PMID 27129149, 2016). "In another study, both IL-1β and TNFα promoted MG-63 osteosarcoma cell adhesion on laminin." (PMID 27556857, 2016). "High OPG levels in a human osteosarcoma cell line are positively correlated with TNFα and suggest that inflammatory cytokines may aid in tumor proliferation by stimulating the production of OPG." (PMID 27136576, 2016). "TNFα was reportedly required for osteosarcoma progression in mice." (PMID 27129149, 2016).
osteosarcoma (continued). "Since TNF-α was reported to be able to confer anti-tumor effects and was also produced by both LPS + IFN-γ–activated and L-MTP-PE + IFN-γ–activated M1-like macrophages during the co-culture, a role for TNF-α in the inhibition of osteosarcoma cell growth was examined." (PMID 24612598, 2014). "Liposomal muramyl tripeptide phosphatidylethanolamine is an activator of monocytes and macrophages and induces the secretion of different cytokines (Interleukin 1[IL 1], IL 6, tumor necrosis factor α [TNFα]), and it has been tested in clinical studies on osteosarcoma patients." (PMID 18782081, 2008). "Hence, to abnormalize the function of the TNF signaling pathway might be a potential target for chemotherapy of advanced osteosarcoma." (PMID 32665038, 2020). "However, SCID mice have lower levels of TNFα than wild type mice, and since osteosarcoma cells were only sensitive to Smac mimetics in vitro when co-treated with TNFα, the SCID xenograft model may underestimate the efficacy of LCL161." (PMID 31521127, 2019). "Osteosarcomas harbor a large population of macrophages that could secrete TNFα, and implantation of transformed mesenchymal cells into mice produced osteosarcomas that were infiltrated by TNFα-expressing macrophages." (PMID 31521127, 2019). "Whether Sirt6 is regulated by NFκB in this system remains to be explored, however, global profiling of p65 binding sites (by ChIP-seq) in TNFα-induced human osteosarcoma U-2 OS cells and TNFα-induced or poly(I:C) stimulated Detroit 562 cells did not identify SIRT6 as a NFκB/p65 target gene." (PMID 30886604, 2019). "In addition, we found that the TNF‐α/NF‐κB/CUL4B axis was activated in osteosarcoma cells." (PMID 29377600, 2018). "Thus the presence of local TNFα probably promotes osteosarcoma expansion and invasion, but could also be exploited therapeutically, if it could cooperate with IAP antagonists to promote tumor cell death." (PMID 27129149, 2016). "Network pharmacology showed that 251 luteolin against osteosarcoma targets and 8 hub targets including AKT1, ALB, CASP3, IL6, JUN, STAT3, TNF, and VEGFA." (PMID 40066267, 2025). "For instance, a constant activation of NFκB, a reduced apoptosis after cell treatment with TNF-α and an increased metastatic potential were shown in VCP/p97 transfected osteosarcoma cells." (PMID 41357812, 2025). "The NF-κB pathway significantly affected by inflammatory cytokines during chemotherapy, especially in osteosarcoma, where the TME is abundant in pro-inflammatory cytokines such as TNF-α, IL-6, and IL-1." (PMID 39949765, 2025). "In summary, UBE2O promotes osteosarcoma progression by degrading L3MBTL2, disrupting its nuclear condensates, derepressing IFIT2 transcription, and activating the TNF/NF-κB pathway." (PMID 40426910, 2025). "Another study indicated that overexpression of DAP-1 induces apoptosis in the TNF-sensitive L929 fibroblast cell line, as well as in the TNF-resistant U2OS osteosarcoma cell line." (PMID 39346724, 2024). "Previous reports have shown that the cytokines VEGF, IL-17, IL-6, IL-8, IL-1Ra, TNF-α, IL-34, and TGF-β play a role in the development of osteosarcoma." (PMID 35102149, 2022). "Through detecting cytokine release in the supernatant after co-incubation for 18 h, we found that CAR-T cells in the B7-H3-positive osteosarcoma cell group significantly released cytokines including IFN-γ and TNF-α." (PMID 36320072, 2022). "Previous studies have suggested that transcription factors OCT‐1, AP1, SP1, TNF, SOX2, SOX4, and MYC play an important role in the proliferation of osteosarcoma cells." (PMID 34185412, 2021). "It was also found that the tumor necrosis factor (TNF) signaling pathway, which is always activated in human osteosarcoma cells, was significantly correlated to osteosarcoma metastasis." (PMID 32665038, 2020).